CD4 (CD4 molecule)
Diseases named in the same sentence as CD4 in open-access papers (continued):
Sharing a sentence is not in itself a finding about the gene and the disease.
infection (continued). "In summary, establishing novel roles for SHH and NOTCH1 signaling pathways, we found mycobacteria-activated SHH signaling induces PD-L1 and COX-2-PGE2 to mediate the expansion of CD4+CD25+FoxP3+ Tregs whereas infection-induced NOTCH1 signaling was found to suppress the Treg expansion." (PMID 27080341, 2016). "It remains to be determined whether CXCR4 binding by R3A Env also contributes to CD4 T cell death during infection." (PMID 27026376, 2016). "First, to evaluate whether thymic content of tTregs (detected as Foxp3+ cells inside CD4+ single-positive -CD4 SP- compartment) were affected, we monitored by cytofluorometry their frequency and cell number during infection in C57BL/6 mice." (PMID 26745276, 2016). "While intracellular viral Ag could represent intracellular infection or receptor-mediated uptake, transfer of sera alone led to superior CD4 T cell recall responses upon in vitro stimulation, supporting the latter scenario." (PMID 27849030, 2016). "Similarly to previous reports, we found that a greater proportion of CD38+ CD4+ T cells expressed CD45RA in comparison to CD38- CD4+ T cells both prior to, and at peak infection." (PMID 27662621, 2016). "Based on a previously observed association between symptomatic WNV infection and reduced Tregs, subjects with neuroinvasive disease could be expected to have stronger WNV-specific CD4+ T cell responses than those with asymptomatic infection." (PMID 26795118, 2016). "Lastly, the variables included in our research design were limited, as other aspects could contribute to HRQoL prediction, such as satisfaction with care, adherence, substance use, viral load, CD4 count, stage of infection, time since diagnosis or comorbidity." (PMID 27809839, 2016). "Whether the presence of low dose IL-2 enhanced the level of integration and infection observed in resting CD4+ T-cells is unclear." (PMID 27383184, 2016). "However, CD4+ T cell depletion was shown to abrogate the protection against Ct-infection more profoundly than the depletion of CD8+ T cells." (PMID 27636704, 2016). "Nevertheless, based on the descriptions of very extensive CD4+ T cell depletion in GALT during primary infection, and also dysfunction of GCs, we hypothesized that Tfh were irreversibly lost." (PMID 27822211, 2016). "After the first 4 weeks of infection, CD4+ T, CD8+ T and natural killer (NK) cells recover their capacity to produce IFNγ, thus promoting the macrophage microbicidal activity with NO synthesis and control of granuloma formation in liver (see next paragraph) and ultimately parasite burden reduction." (PMID 26969511, 2016). "To investigate whether our findings are specific to vaccination with fungi or apply to other classes of microbes, we studied the contraction of LCMV primed CD4+ T cells after infection." (PMID 27542117, 2016). "Notably, CD4+YFP+ T cells were the major source of IL-10 during secondary infection in all examined organs, implying that memory CD4+ T cells rapidly expanded and expressed IL-10 during secondary infection." (PMID 27630165, 2016). "Thus, it is possible that the MalE constructs of these peptides recruit a subset of CD4 T cells of somewhat higher affinity than those generated by infection." (PMID 27329272, 2016). "Importantly, several additional cytokines and chemokines secreted by CD4+ T cells, including IL-17 and IL-6, are proinflammatory and capable of recruiting immune cells to the genital tract during infection." (PMID 27600502, 2016). "However, due to losses in splenic CD4+ T cells during infection, the total lymphocyte percentage remained the same (first panel)." (PMID 28066416, 2016).
infection (continued). "Macrophages are able to selectively capture HIV-1-infected CD4+ T-cells leading to the infection and efficient transfer of HIV-1 from cell-to-cell These cells are found in surfaces typical of the meatus (distal end of penile urethra), fossa navicularis (opening), and foreskin." (PMID 27446076, 2016). "Moreover, whereas Ag-experienced CD4+ T cells obtained on day 60 of infection produced only marginally less IFN-γ, they produced significantly less IL-10 than did counterpart cells obtained from day 7 of infection." (PMID 27630165, 2016). "CD4+- as well as CD8+-deficient C57BL/6 survived the infection without showing symptoms of disease at any point in time." (PMID 27875529, 2016). "Whether microbiota-driven γδT cells or adaptive CD8+, CD4+ T cells are critical in regulating PMN recruitment during infection in the ocular mucosa remains to be clarified." (PMID 27658245, 2016). "In agreement with this, using a murine model, we demonstrated that infection with seasonal H1N1 established substantial numbers of memory CD4 T cells that could be mobilized and provide protection upon infection with the pH1N1 strain." (PMID 26834750, 2016). "Infection led to CD3+CD4+ and CD3+CD8α+ lymphocyte infiltration into the magnum of the oviduct." (PMID 27846843, 2016). "In support of this hypothesis, blockade of ICOS from day 3 of infection, which is after CD4+ T cell priming, significantly abrogated the expression of IL-10 by parasite-specific CD4+ T cells in all examined organs." (PMID 26459508, 2016). "This could explain the variation observed in the pre-existing proportion of CD38+ cells among total CD4+ T cells between individuals (ranging from 0.9 to 10.9% of total CD4+ T cells), reflecting a more or less recent infection with a pathogen." (PMID 27662621, 2016). "Infection history analysis showed that C. albicans-specific CD4 T cells were more susceptible to HIV in vivo, harboring modestly but significantly higher levels of HIV DNA, than CMV-specific CD4 T cells." (PMID 27280548, 2016). "Furthermore, Ctsl-/- mice had profound deficits in CD4+ lymphocytes before and after infection and weaker production of pathogen-specific IgG." (PMID 27716790, 2016). "In macaques, we didn’t detect a higher rate of infection in CXCR3+ versus CXCR3neg CD4+ cells." (PMID 27509048, 2016). "Interestingly, the ablation of CCR5 binding in R3A-5/6AA infection completely rescued death of p24(−) bystander CD4 T cells to background levels." (PMID 27026376, 2016). "For mild infections, whether caused by seasonal influenza viruses or occasional asymptomatic AIVs, the pre-existing CD8+ and/or CD4+ T cells can provide a great level of protection." (PMID 26973644, 2016). "Likewise, and in keeping with viral propagative infection, B-EnvEC and B-Env virions produced from CD4+ T-cells comparably infected TZM-bl cells in the single-round infection assay." (PMID 27598717, 2016). "However, this decline was stronger in CD4-Cre A20fl/fl mice and, upon secondary infection, the increase of Lm OVA-specific CD8+ T cells was significantly impaired as compared to A20fl/fl control mice." (PMID 28004776, 2016). "R3A infection reduced the viabilities of both p24(−) and p24(+) CD4 T cells." (PMID 27026376, 2016). "Recent data suggest that while IFNα and pDCs do indeed limit HIV-1/SIV levels during early infection, they may also promote CD4 T cell depletion at later times, possibly due to IFNα-induced upregulation of apoptosis." (PMID 27010978, 2016). "However, this protective effect of CD4+ T cells was lost during infections with higher doses of S. suis and at later time points." (PMID 27905502, 2016). "In this study, we investigated the impact of representative bacterial species that were altered in the colonic mucosa of viremic HIV-1 infected individuals (HIV-altered mucosal bacteria; HAMB) on intestinal CD4 T cell function, infection by HIV-1, and survival in vitro." (PMID 26762145, 2016).
infection (continued). "In comparison, CD4+ T cell-depleted mice less successfully controlled infection." (PMID 27892938, 2016). "Although an increase in frequency of circulating CD38+ CD4+ T cells has been observed following immunization or infection in a number of host-pathogen systems, the role of those cells has not been elucidated, and impaired cytokine capacity has not been reported." (PMID 27662621, 2016). "Additionally, the CD38+ CD4+ T cells contained a higher proportion of cells co-expressing perforin and granzyme B (p = 0.001 and p = 0.006 prior to and at peak infection, respectively." (PMID 27662621, 2016). "One chimpanzee, who had a broader T-cell response during initial infection, did respond to PD-1 blockade, with expansion and broadening of both CD4+ and CD8+ T-cell responses coinciding with a significant drop in viral load, which rebounded on withdrawal of the blockade." (PMID 27490575, 2016). "Thus, not only is the B-cell response to infection helped and clonally diversified by CD4+ T cells, it also reciprocally helps and clonally diversifies the CD4+ T-cell response." (PMID 26728651, 2016). "Intracellular cytokine staining and flow cytometric analysis demonstrated a significant decrease in the proportion and absolute number of IL‐17+ CD4+ T cells in NK cell‐depleted mice compared with control mice in spleen, lung and mediastinal lymph node cells on day 6 and 12 after infection." (PMID 27028780, 2016). "Whether this pathway is connected to GSK-3 regulation of PD-1 in effector CD8+ T cells is unclear because we failed to observe an effect of GSK-3 inactivation on PD-1 expression on CD4+ T cells during LCMV-Cl13 infection." (PMID 26885856, 2016). "The kinetics of granzyme B-producing CD8+ T cells complemented the characteristic of the IFN-γ kinetics with increased numbers and MFI of granzyme B+ cells in CD4-Cre A20fl/fl mice in primary infection at day 7 p.i. but reduced numbers and MFI in reinfected mice at day 53 p.i.." (PMID 28004776, 2016). "The severely immunocompromised CD4-depleted μMT mice were unable to resolve infection." (PMID 27600502, 2016). "Infection is quantified by measuring the amount of viral DNA in cells isolated from tissues; however, this approach overestimates the number of productively infected CD4+ T cells due to the presence of a large proportion of defective proviruses in vivo." (PMID 27030272, 2016). "Furthermore, emerging literature suggests that full CD4 T cell differentiation occurs at sites of infection and inflammation after they have migrated from the secondary lymphoid organs." (PMID 27280403, 2016). "The fact that FTY720 enhanced the frequency of cells producing both TNFα and IFNγ, in MAITs, CD8 T cells, and CD4 T cells, while declining that of TNFα single-producer cells in CD4 T cells suggested beneficial effects of FTY720 on the host defense against infection." (PMID 27536542, 2016). "Moreover, inoculation of log-phase parasites led to better activation of lymph node CD4+ T cells (IFNγ production) than inoculation of metacyclic promastigotes, at least during the early stages of infection (16 h and 3 days post-inoculation)." (PMID 26969511, 2016). "Moreover, CD4+YFP+GFP− T cell–derived memory cells rapidly upregulated IL-10–GFP expression in the spleen during challenge infection, leading to a significant increase in generation of new CD4+YFP+GFP+ T cells in the spleen during secondary infection." (PMID 27630165, 2016). "Additionally, exosomes derived from infected dendritic cells (DCs) have a profound enhancing effect on CD4+ T cell infection." (PMID 26981123, 2016). "However, PD-1 expression in Foxp3+CD4+ T cells was significantly decreased at three weeks post-infection and increased since eight weeks post-infection." (PMID 27792733, 2016). "The contribution of CD4+ T cells to infection and disease progression has been extensively studied." (PMID 27030272, 2016).
infection (continued). "Second, we performed adoptive T cell transfer into R. typhi-infected C57BL/6 RAG1-/- mice to show whether CD8+ and CD4+ T cells would still be protective in an established R. typhi-infection." (PMID 27875529, 2016). "Likewise, IFN-γ and IL-17 signaling blockade or CD4+ T cell depletion eliminated the genital pathology produced in untreated controls by multiple ivag challenge infections." (PMID 27606424, 2016). "We consequently questioned whether ICOS plays a role in the subsequent stabilization or maintenance of IL-10 expression by CD4+ T cells during infection potentially downstream of the IL-27R-dependent induction of IL-10 expression." (PMID 26459508, 2016). "Interestingly, it has been shown recently that dendritic cells exposed to free HTLV-1 particles not only become productively infected themselves (cis-infection), but can also rapidly transmit the virus to CD4+ T-cells (trans-infection)." (PMID 27322308, 2016). "Thus, we are certain that the HIV-1 integration sites amplified from CD4+ T cells after two days of activation and a further two days of ex vivo infection were the result of these ex vivo infections." (PMID 27067385, 2016). "Burn injury caused decline in CD4+ and CD8+ T cells in the spleen, which was worsened by infection." (PMID 26859674, 2016). "The main function of IL-10 during primary infection appears to be inhibition of MHC II expression by APCs and innate cells, whereas during secondary infection its primarily role appears to be controlling T cell responses and, putatively, the early reactivation of memory CD4+ T cells." (PMID 27630165, 2016). "The microbicidal capability of macrophages co-cultured with CD4+ or CD8+ T-cells or CD4+:CD8+ T-cells simultaneously was assessed after in vitro infection with L. infantum and the cytokine levels were analyzed from dogs after 24 months of the experimental challenge with L. infantum." (PMID 27136900, 2016). "However, the exact kinetics and the role of CD8+ or CD4+ T cell responses in the recovery from infection, especially severe AIV infection, is not well understood." (PMID 26973644, 2016). "Moreover, CD4 T cells can engage in direct cytotoxicity of antigen bearing cells, a function suggested to be the primary correlate of protection from infection in humans." (PMID 26834750, 2016). "In order to further distinguish whether CD4+ T lymphocytes were the only immune cells involved in the anti-infection effect by X-ray irradiated vaccine in vivo, CD4+ or CD8+ T lymphocytes were depleted independently by corresponding antibodies." (PMID 26879055, 2016). "Interestingly, however, the balance between GFP+ and GFP− cells within the (disparately sized) CD4+ YFP+ T cell populations achieved parity in all examined tissues by day 7 of infection." (PMID 26459508, 2016). "Similarly, in another controlled infection experiment, a strong protective role for memory CD4+ T cells was elucidated." (PMID 27754364, 2016). "Direct infection of resting CD4+ T cells in vitro is inefficient." (PMID 27459960, 2016). "In addition, evaluation of the immune cell populations in the lungs following secondary infection showed a significant increase in the number of CD8+ T-cells and CD19+ B-cells in animals depleted of CD4+ T-cells prior to a secondary infection." (PMID 27242785, 2016). "Since HIV-1 entry takes place in lipid rafts of the plasma membrane, we examined whether pH1N1 infection affects CD4 expression on the plasma membrane in Jurkat cells infected with HIV-1 and pH1N1." (PMID 26848681, 2016). "Finally, we investigated the cell subset precursor of the CD38+ CD4+ T cells that expanded in vivo upon infection." (PMID 27662621, 2016). "HIV-1 entry across epithelial or endothelial barriers as well as transplacental infection might thus be HS dependent, and it will be of interest to investigate whether the CD4-conjugate molecules could interfere with these processes." (PMID 27721488, 2016).
infection (continued). "Studies on the distribution of latent HIV in different CD4+ T cell subsets demonstrated an about 10-fold higher infection frequency of memory versus naïve T cells and a major contribution of infected central memory and effector memory T cells to the total HIV-1 reservoir." (PMID 27990142, 2016). "Compared with normal uninfected control mice, significantly higher levels of Fas and PD-L1 were detected on splenic and mesenteric CD4+ T cells of S. japonicum-infected mice eight weeks post-infection, suggesting that CD4+ T cells tend to be anergic in S. japonicum infection." (PMID 27792733, 2016). "The Ras/Raf/MEK pathway has previously been associated with the nuclear import of the HIV reverse transcriptase complex (RTC) and thus may enhance HIV nuclear entry required for infection of resting CD4+ T cells." (PMID 27459960, 2016). "Furthermore, this robust virus replication resulted in a significant depletion of peripheral CD4+ T cells during the acute SIVsmmFTq infection and a partial CD4+ T cell restoration during chronic infection." (PMID 27632364, 2016). "To clarify the contribution of CD8-positive T cells to the Th17 bias that we observed in this infection model, the IL-17 production was evaluated in the CD4-positive T cells and CD8-positive T cells obtained from the lungs of WT mice and RORγt-tg mice 2 months following MAC infection." (PMID 26784959, 2016). "Some experiments have confirmed that removing or reducing CD4+CD25+ Tregs could enhance the host anti-infection immunity to several pathogens." (PMID 26901645, 2016). "On the other, proliferating CD4+ T cells are main targets for infection and viral replication." (PMID 27379092, 2016). "Therefore, we first examined ICOS expression by CD4+ T-cells during Py17XNL infection, revealing significant up-regulation by 5–7 days p. i., which progressively increased over the following 7–9 days." (PMID 27812214, 2016). "We show that the levels of parasite burden following experimental P. falciparum blood-stage infection inversely correlated with the expansion of a specific subset of CD4+ T cells expressing CD38 and characterized by high cytotoxic potential but impaired cytokine production." (PMID 27662621, 2016). "Similarly to ex vivo data, a significant production of IL-10 by CD4+ cells was also observed in vivo during S. suis primary infection." (PMID 27905502, 2016). "Thus, it is possible that activated NK cells in E. muris- primed mice promote the induction/ maintenance of central memory CD4+Th1 cells, and/or expansion of effector memory CD4+Th1 cells following second IOE infection." (PMID 27092553, 2016). "Thus, memory CD4 T cells and circulating antibody can both be involved in effective clearance of bacteria during secondary infection." (PMID 27999159, 2016). "Therefore, clonotypic replacement of Vα2 virus-specific CD4+ T cells over the course of infection required cognate T cell–B cell interaction." (PMID 26728651, 2016). "Interestingly, in our cohort, in contrast to the association with high viral load, the development of bnAb responses significantly correlated with low CD4 T cell counts only at later time points, past 6 months of infection." (PMID 26766578, 2016). "Furthermore, R3A infection resulted in higher cell death of p24(-) CD4 T cells than R3A-5/6AA infection in vivo." (PMID 27026376, 2016). "Moreover, repeated infections resulted in the development of CD4+ T cell hypo-responsiveness in the skin-draining lymph nodes (sdLN), as well as decreased immunopathology in the liver generated in response to eggs released by adult worms." (PMID 27505056, 2016). "The fate of these CD4+IFN-γ+IL-10+ T cells following clearance of primary infection and their subsequent influence on the course of repeated infections is, however, presently unknown." (PMID 27630165, 2016).